SOST (sclerostin)
Diseases named in the same sentence as SOST in open-access papers (continued):
Sharing a sentence is not in itself a finding about the gene and the disease.
differentiated thyroid carcinoma (1 paper, 2021). Differentiated thyroid carcinoma (DTC), also known as papillary or follicular thyroid carcinoma, is a slow-growing malignancy usually presenting in adults as an asymptomatic thyroid mass. "We evaluated the effect of recombinant human TSH (rhTSH) on sclerostin and other bone markers in 29 patients after total thyroidectomy for differentiated thyroid cancer (DTC), without any signs of disease recurrence, who received L-thyroxine, most at non-suppressive doses." (PMID 34768424, 2021).
dysplasia (1 paper, 2023). A usually neoplastic transformation of the cell, associated with altered architectural tissue patterns. "BMP3 and SOST are potential biomarkers for IBD with dysplasia or CAC and axial SpA/IBD, respectively; however, other BMP-relevant molecules may also have the potential to be novel biomarkers in IBD patients." (PMID 37391444, 2023).
fatty liver (1 paper, 2021). "Circulating sclerostin was also negatively correlated with fatty liver index in NAFLD subjects but not in control subjects." (PMID 34421825, 2021).
Gestational Diabetes Mellitus (1 paper, 2023). "This study aims at evaluating the expression of placental LRP5 and sclerostin in pregnancies with gestational diabetes mellitus (GDM) and investigate possible associations with umbilical sclerostin concentrations and clinical outcomes in mothers and their neonates." (PMID 36947076, 2023).
gingivitis (1 paper, 2021). A disorder involving inflammation of the gums; may affect surrounding and supporting structures of the teeth. "The total amounts of Sclerostin and WNT-5a in GCF samples of individuals with a healthy periodontium, gingivitis and generalized periodontitis were evaluated in this study." (PMID 34440994, 2021). "Considering the literature, this is the first investigation to address the total protein amounts of SOST and WNT-5a in gingivitis sites." (PMID 34440994, 2021).
Glucose intolerance (1 paper, 2022). Glucose intolerance (GI) can be defined as dysglycemia that comprises both prediabetes and diabetes. "Therefore, glucose intolerance in older patients with SCI can increase sclerostin levels." (PMID 35742035, 2022).
Granuloma (1 paper, 2025). A compact, organized collection of mature mononuclear phagocytes, which may be but is not necessarily accompanied by accessory features such as necrosis. "SOST expression is correlated with the severity of inflammation and granulomas in the liver and gallbladder, and serum SOST levels in patients with early stage BPC show a decreasing trend over time." (PMID 40563496, 2025).
hematoma (1 paper, 2024). A hematoma is a collection of blood from a vascular structure into an extravascular space. "While DKK1 levels strikingly decreased in facture hematoma, we found SOST levels significantly elevated at this early stage of fracture healing." (PMID 38499638, 2024). "As we observed a close inverse correlation of DKK1 and SOST in human fracture hematoma as well as during the fracture healing time course, our data would suggest that also in humans dual inhibition of DKK1 and SOST would most likely be critical to improve fracture healing." (PMID 38499638, 2024).
Hypercalciuria (1 paper, 2024). "As hypercalciuria is one of the most relevant risk factors for kidney stones, sclerostin might possess pathogenic relevance in nephrolithiasis." (PMID 38186870, 2024). "Consequently, increased levels of sclerostin might cause hypercalciuria." (PMID 38186870, 2024). "Sclerostin levels were increased in rKSF independent of hypercalciuria and significantly associated with the status as rKSF." (PMID 38186870, 2024).
hyperhomocysteinemia (1 paper, 2024). A serious metabolic condition caused by mutations in the MTHFR gene, medications, or nutritional deficiency. "By studying SOST in osteoclasts derived from RAW 264.7 macrophages, the research aimed to explore taurine's effect on mitigating excessive bone resorption, particularly in a pro-osteoclastogenic environment influenced by hyperhomocysteinemia." (PMID 39707534, 2024).
hyperparathyroid bone disease (1 paper, 2019). "Thus, the Wnt signaling pathway protein sclerostin seems to be associated with the pathogenesis of hyperparathyroid bone disease." (PMID 31477034, 2019). "We hypothesized that the secreted Wnt antagonists sclerostin and DKK1 may play a role in the regulation of hyperparathyroid bone disease and in the process of vascular calcification in patients on dialysis with severe SHPT." (PMID 31477034, 2019).
Hypocalcemia (1 paper, 2021). An abnormally decreased calcium concentration in the blood. "Limited clinical evidence suggests that the osteoanabolic and anti-resorptive activity is attenuated, but hypocalcemia is more prevalent in patients with advanced CKD (eGFR < 30 mL/min) treated with anti-sclerostin (romosozumab) therapy as compared to patients without kidney disease." (PMID 34822428, 2021).
idiopathic hypercalciuria (1 paper, 2024). A rare renal disease characterized by persistent excess urinary calcium excretion in the absence of an underlying systemic disease and hypercalcemia. "Menon and others assessed local expression of sclerostin in stone-forming patients with idiopathic hypercalciuria (IH) by immunostaining of undecalcified bone." (PMID 38186870, 2024).
idiopathic osteoporosis (1 paper, 2020). "A study on male idiopathic osteoporosis reported that lower sclerostin expression could reflect an autoregulatory promotion of bone formation." (PMID 31912287, 2020).
idiopathic scoliosis (1 paper, 2021). A scoliosis with no known cause. "Osteocytes from bone biopsies of patients with idiopathic scoliosis had decreased SOST gene expression as well as lower sclerostin secretion." (PMID 34830568, 2021). "The present review article summarizes the current knowledge on sclerostin structure, expression, and regulation and also discusses its role in the pathogenesis of idiopathic scoliosis." (PMID 34830568, 2021). "One possible explanation of sclerostin downregulation in patients with idiopathic scoliosis is through the cadmodulin/calcitonin interaction." (PMID 34830568, 2021). "Osteocytes derived from CTNNB1 knocking down osteoblasts from patients with idiopathic scoliosis SOST gene expression and sclerostin secretion were found significantly elevated." (PMID 34830568, 2021). "Wnt/β-catenin signaling pathway overexpression and sclerostin downregulation by osteocytes could be progressive factors for the development of idiopathic scoliosis." (PMID 34830568, 2021). "Furthermore, sclerostin expression was found decreased, while β-catenin was overexpressed in bone lining cells derived from patients with idiopathic scoliosis." (PMID 34830568, 2021). "Decreased levels of sclerostin may be explicated due to elevated levels of miRNAs in bone biopsies from idiopathic scoliosis patients." (PMID 34830568, 2021). "Serum level of SOST was negatively correlated with plasma miR-145, and serum level of SOST miR-145 knockdown in osteoblasts from idiopathic scoliosis patients improved osteocyte function possibly by maturation of osteocytes and dendrite formation and not by osteoblast differentiation." (PMID 34830568, 2021).
Impaired glucose tolerance (1 paper, 2020). An abnormal resistance to glucose, i.e., a reduction in the ability to maintain glucose levels in the blood stream within normal limits following oral or intravenous administration of glucose. "In addition, high levels of sclerostin in serum were associated with impaired glucose tolerance, suggesting a potential role of bone‐derived sclerostin in the regulation of glucose metabolism." (PMID 32161838, 2020).
injury (1 paper, 2023). Damage inflicted on the body as the direct or indirect result of an external force, with or without disruption of structural continuity. "The original study showed a direct correlation between BMD and sclerostin concentration, in groups of healthy women and in people with spinal cord injury, and posited that sclerostin concentration could complement or even replace densitometric testing." (PMID 37371669, 2023).
kidney stone (1 paper, 2024). "We performed a prospective cross-sectional observational controlled study in 150 recurrent kidney stone formers (rKSF) to analyse the association of sclerostin with known stone risk factors and important modulators of calcium-phosphate metabolism." (PMID 38186870, 2024). "The aim of this study was to assess if sclerostin or FGF23 are associated with derangements of mineral metabolism or other metabolic or demographic factors in our cohort of recurrent kidney stone formers (rKFs)." (PMID 38186870, 2024). "Our results need to be confirmed in larger stone cohorts to provide evidence if and through which mechanisms sclerostin has an impact on the pathophysiology of recurrent nephrolithiasis." (PMID 38186870, 2024). "Even though a dysregulation of calcium phosphate metabolism is postulated in idiopathic calcium stone formers, no prospective or controlled studies have been performed yet on the potential role of sclerostin in nephrolithiasis." (PMID 38186870, 2024). "Female kidney stone formers had higher weight and BMI compared to controls and BMI interacts with sclerostin." (PMID 38186870, 2024). "Sclerostin levels were increased in rKSF compared to controls and logistic regression exhibited a statistically significant relationship between serum sclerostin and kidney stone formation." (PMID 38186870, 2024). "The effects of sclerostin on bone turnover and calcium metabolism suggest a potential role of this molecule also in other disorders where bone and calcium homeostasis may be disarranged, such as nephrolithiasis." (PMID 38186870, 2024). "In our prospective controlled study, we investigated sclerostin and FGF23 in rKSFs and controls to test their potential role in recurrent kidney stone formers." (PMID 38186870, 2024). "In this cohort, mean sclerostin plasma levels in control patients with negative history for kidney stones was 632 ± 263 pg/ml." (PMID 38186870, 2024). "This might indicate a potential role of sclerostin in kidney stone formation, notably, independent of urinary calcium excretion." (PMID 38186870, 2024).
lysosomal storage disorders (1 paper, 2021). "Our data support the exploration of therapeutics that target sclerostin to treat low bone mass symptoms in patients with lysosomal storage disorders." (PMID 33779549, 2021).
metastatic prostate carcinoma (1 paper, 2018). A carcinoma that arises from the prostate gland and has spread to other anatomic sites. "Dickkopf-1 (DKK-1) and sclerostin seem to inhibit osteoblast activity by blocking the Wnt pathway, which leads to progression of metastatic prostate cancer (PC)." (PMID 30116403, 2018).
Moyamoya disease (1 paper, 2025). Moyamoya disease (MMD) is a rare intracranial arteriopathy involving progressive stenosis of the cerebral vasculature located at the base of the brain causing transient ischemic attacks or strokes. "RGS1, MUC1, KCNA2, TAC1, and SOST were all found to be up-regulated in moyamoya disease." (PMID 40462179, 2025).
multinodular goiter (1 paper, 2022). Nodular goiter characterized by more than one discrete tissue mass. "In two studies published by the same group, sclerostin levels were determined in patients of both genders diagnosed with GD or multinodular goiter at the time of diagnosis and 6–10 weeks after ATD initiation." (PMID 36005583, 2022).
nephritis (1 paper, 2021). Inflammation of renal tissue. "SOST level can provide a reference for the severity of nephritis and other diseases, elevated serum SOST is a risk factor for kidney disease." (PMID 34901023, 2021).
ocular tumors (1 paper, 2022). "The results showed that when SOST expressions were knocked down in human UM cells, the tumor volume of ocular tumors of nude mice was larger." (PMID 35785219, 2022).
primary adrenal insufficiency (1 paper, 2022). A hormonal disorder that occurs when the adrenal glands fail to release adequate amounts of glucocorticoids (cortisol), mineralocorticoids (aldosterone, 11-deoxycorticosterone), and androgens (dehydroepiandrosterone) to meet physiologic needs, despite release of ACTH from the pituitary. "There was a significant correlation between serum sclerostin and fT4 concentration in patients with primary adrenal insufficiency." (PMID 36407318, 2022). "We have found that in patients with Addison`s disease the serum sclerostin concentration was significantly higher than in the control group (p=0.006)." (PMID 36407318, 2022). "The aim of the study was to evaluate densitometry parameters, trabecular bone score and sclerostin concentrations in patients with primary adrenal insufficiency in comparison to control group." (PMID 36407318, 2022). "The strength of our work is the homogeneity of our study group (autoimmune etiology of the disease, treatment with hydrocortisone) and the use of novel methods (first report of TBS and sclerostin in Addison`s disease)." (PMID 36407318, 2022). "Since this is the first study concerning sclerostin in Addison’s disease, it is difficult to draw conclusions why sclerostin was higher in patients than in controls." (PMID 36407318, 2022). "TBS results were not impaired in patients with Addison`s disease while sclerostin concentrations were significantly increased in comparison to healthy subjects." (PMID 36407318, 2022).
renal cell carcinoma (1 paper, 2016). "As renal cell carcinoma (RCC) patients often present with osteolytic metastases, we aimed to investigate serum sclerostin levels in RCC patients." (PMID 27666393, 2016).
sacroiliitis (1 paper, 2015). "In multivariate analysis, DKK-1 serum levels were associated with male gender (p = 0.03), CRP level (p = 0.006), SOST serum level (p = 0.002) and presence of sacroiliitis on radiography (p = 0.05)." (PMID 26313358, 2015). "Multivariate analysis revealed a significant positive association of DKK-1 serum level and female gender (p = 0.03), CRP level (p = 0.006), SOST serum level (p = 0.002) and the presence of sacroiliitis on radiography (p = 0.05)." (PMID 26313358, 2015). "SOST serum level in axial SpA patients was lower for those with than without sacroiliitis on radiography (n = 130 vs. n = 346; mean 42.95 ± 18.4 vs 49.25 ± 28.91 pmol/L; p = 0.023)." (PMID 26313358, 2015).
schizophrenia (1 paper, 2023). A major psychotic disorder characterized by abnormalities in the perception or expression of reality. "It has been reported that plasma levels of soluble dickkopf 1 (DKK-1) and sclerostin are significantly lower in schizophrenia than in healthy controls." (PMID 36680208, 2023).
scrub typhus (1 paper, 2021). Scrub typhus is a rare dust mite-borne infectious disease caused by the Orientia tsutsugamushi bacterium and characterized clinically by an eruptive fever which is potentially serious. "In contrast, SOST, which was increased in both scrub patients and infectious controls, was strongly associated with poor prognosis in scrub typhus patients and were strongly correlated with markers of macrophage and endothelial cell activation." (PMID 33914733, 2021). "First, we observed a strong positive correlation between SOST levels in patients with scrub typhus and creatinine and accordingly, patients with eGFR<60 had markedly higher SOST levels." (PMID 33914733, 2021). "At recovery (median 17 days, range 5–135) after the initial sample, scrub typhus patients had a significant decrease in SOST and increase in DKK-1 levels compared to admission levels, reaching levels comparable to healthy controls." (PMID 33914733, 2021). "Taken together, we hypothesize that SOST could be involved in vascular dysfunction in severely ill scrub typhus patients, involving effects on monocytes/macrophages and endothelial cells." (PMID 33914733, 2021). "We found i) Levels of SOST and in particular sFRP-3 and WIF-1 were markedly increased and DKK-1 decreased in scrub typhus patients at admission to the hospital compared to healthy controls." (PMID 33914733, 2021). "Levels of SOST and in particular sFRP-3 and WIF-1 were markedly increased in scrub typhus patients at admission to the hospital compared to healthy controls and notably for sFRP-3 and WIF-1, also when compared to admission levels in infectious controls." (PMID 33914733, 2021). "We hypothesized that plasma levels of the secreted Wnt modulators sFRP-3, DKK-1, SOST and WIF-1 would be regulated in scrub typhus and correlate with markers of inflammation and immune activation." (PMID 33914733, 2021).
Sepsis (1 paper, 2023). Sepsis is defined as life-threatening organ dysfunction caused by a dysregulated host response to infection. "Over time changes in SOST levels during sepsis and their association with outcomes—mainly time-to-event—further highlight a potential role of SOST as an acute-phase protein." (PMID 36943596, 2023). "In line, high baseline/persistently high SOST levels would sustain mortality risk through a dysregulated host response, in accordance with the third international consensus definitions for sepsis and septic shock (Sepsis-3)." (PMID 36943596, 2023). "In conclusion, the present study provides preliminary evidence for a prognostic role of SOST in sepsis." (PMID 36943596, 2023). "Here, we preliminarily focused on sclerostin (SOST) as a candidate biomarker to encompass such a broad range of clinical needs related to sepsis." (PMID 36943596, 2023). "Especially high baseline/persistently higher circulating levels of SOST may predict short- and long-term mortality in elderly patients with sepsis admitted in internal medicine wards." (PMID 36943596, 2023). "Nevertheless, variations in time course and their prognostic relevance allowed us to hypothesize SOST as not innocent bystander in sepsis." (PMID 36943596, 2023).
Splenomegaly (1 paper, 2025). Abnormal increased size of the spleen. "We also observed significantly higher sclerostin concentrations in patients with splenomegaly (34.2 vs. 19.7 [pmol/l])." (PMID 39747949, 2025).
systemic mastocytosis (1 paper, 2024). Systemic mastocytosis (SM) comprises a heterogeneous group of rare acquired and chronic hematological malignancies that are related to an abnormal proliferation of mast cells in tissue, including bone marrow, with or without skin involvement. "Recent, albeit inconsistent, reports have indicated increased levels of sclerostin or DKK1 in patients with indolent systemic mastocytosis." (PMID 39596937, 2024). "Furthermore, serum levels of sclerostin and 25-hydroxyvitamin D have been found to be negatively correlated, indicating that vitamin D levels may play a crucial role in determining sclerostin levels in patients with systemic mastocytosis." (PMID 39596937, 2024).
thyroid (1 paper, 2020). "Moreover, sclerostin was positively associated with osteocalcin (r=0.605, p=0.005) and beta-cross-laps levels (r=0.573, p=0.008) in all thyroid patients." (PMID 33312059, 2020). "There were positive relationships between circulating concentrations of sclerostin and markers of bone metabolism, i.e. osteocalcin a marker of bone formation and beta-cross-laps marker of bone resorption in all thyroid patients." (PMID 33312059, 2020).
trisomy 21 (1 paper, 2012). A chromosomal disorder consisting of the presence of an extra chromosome 21. "The stimulation of bone mass by intermittent PTH treatment demonstrated the efficacy of the intervention in trisomy 21 and supports the idea that PTH or other potential anabolic treatments, such as anti-sclerostin antibody, may have utility in DS patients with low BMD and low bone turnover." (PMID 22916188, 2012).